RNU6-1143P (RNA, U6 small nuclear 1143, pseudogene)
Gene: Small nuclear RNA gene on chromosome 11 (3,714,772 to 3,714,875, reverse strand). Ensembl gene ENSG00000251934.
Homologues: Orthologues: macaque U6 (91% identical), chimpanzee U6 (67% identical), pig U6 (63% identical), dog U6 (58% identical), guinea pig U6 (51% identical). Paralogues in human: RNU6-188P (77% identical), RNU6-224P (77% identical), RNU6-1289P (76% identical), RNU6-477P (76% identical), RNU6-21P (75% identical), RNU6-46P (75% identical), RNU6-1013P (74% identical), RNU6-10P (74% identical), RNU6-1145P (74% identical), RNU6-1316P (74% identical), RNU6-15P (74% identical), RNU6-20P (74% identical), and 1283 more.